IL6 (interleukin 6)
Diseases named in the same sentence as IL6 in open-access papers (continued):
Sharing a sentence is not in itself a finding about the gene and the disease.
systemic inflammatory response syndrome (continued). "The excessive stress reaction of immune system would release superabundant cytokines such as TNF-α、IL-1、IL-6、IL-12、IFN-α、IFN-γ, leading to systemic inflammatory response syndrome (SIRS) and multiple organ failure." (PMID 34386017, 2021). "TNF-α and IL-6 aggravate SAP and increase plasma extravasation and induce leukocyte adherence, result in SIRS (the systemic inflammatory response syndrome) and MODS (the multiple organ dysfunction syndrome)." (PMID 28713490, 2017). "Although this time-window is identical to the effective time-span in predictive capacity of IL-6 (and other cytokines) for septic deaths, a relatively loose clustering of individual, outcome-based PAI-1 values disqualifies it as a potential stand-alone predictor of outcome in sepsis syndromes." (PMID 23408987, 2013). "The biomarkers IL6, IL8 and PCT appear promising, and should certainly be subject to new primary studies investigating more thoroughly the prediction of significant infectious morbidity, which includes both clearly defined infections and the sepsis syndrome, across a variety of clinical settings." (PMID 22257704, 2012). "For three decades, the production of proinflammatory cytokines, such as IL-1β, IL-6, IL-8, and TNF-α, by leukemic cells in ATRA-differentiated APL patients has been recognized to result in DS and subsequent systemic inflammatory response syndrome (SIRS)." (PMID 41184249, 2025). "SARS-CoV-2 infection can trigger a cytokine storm by activating immune cells, thereby releasing large amounts of cytokines (eg, IL-6 and TNF-α) and leading to systemic inflammatory response syndrome (SIRS) and multi-organ dysfunction (MODS), which often affect the liver." (PMID 39867341, 2024). "IL-6 and MIF had the best predicting value in discriminating mild from severe forms, as well as the development of systemic complications (systemic inflammatory response syndrome—SIRS and multiple organ failure—MOF) and fatal outcomes." (PMID 39125854, 2024). "IL-1β, IL-6, and TNF-α are common proinflammatory factors and are the most influential factors in the development of posttraumatic systemic inflammatory response syndrome (SIRS)." (PMID 37038178, 2023). "The therapeutic strategy by IL-6, IL-1 or TNF-α pathways which could halt or balance the systemic inflammatory response syndrome (SIRS) or the other such complications." (PMID 35008377, 2022). "Fetal inflammatory response syndrome (FIRS) defined as an elevation of either fetal plasma IL-6 or C-reactive protein (CRP) above a specific cutoff value (i.e., IL-6 ≥ 11 pg/mL, CRP ≥ 200 ng/mL) is thought as the fetal counterpart of systemic inflammatory response syndrome (SIRS) in adults." (PMID 34066888, 2021). "In addition, there was an inflammatory cytokine reduction (IL-6 and IL-10), therefore, the BAK had a protective effect from systemic inflammatory response syndrome (SIRS) and multi-organ failure." (PMID 33751266, 2021). "The longitudinal assessment of procalcitonin (PCT) levels, C-reactive protein (CRP) levels, white blood cell count, blood lactate levels, IL-6 levels, Sequential Organ Failure Assessment (SOFA) score, and Systemic Inflammatory Response Syndrome (SIRS) was conducted." (PMID 25705399, 2013). "We did not measure circulating levels of IL-6, CRP and TNF-alpha, but we did look for overt manifestations of inflammation through the systemic inflammatory response syndrome (SIRS) criteria." (PMID 31590379, 2019). "The in vitro release of pro-inflammatory cytokines such as interleukin (IL)-1β, IL-6, IL-8, and tumor necrosis factor-α (TNF-α) have been reported to coincide with ATRA-induced differentiation of APL blasts, which may lead in vivo to a systemic inflammatory response syndrome (SIRS)." (PMID 32859169, 2020). "In patients with severe trauma, elevated plasma concentrations of presepsin in the clinical course were associated with the presence of systemic inflammatory response syndrome (SIRS), whereas PCT and IL-6 did not." (PMID 31261907, 2019).
liver cancer (230 papers, 2009 to 2025). An epithelial or non-epithelial malignant neoplasm that arises from the liver. "Estrogen inhibits IL-6 secretion from liver Kupffer cells and reduces liver cancer risk in females, whose ERα loss also leads to liver cancer." (PMID 40568073, 2025). "IL6 is a pleiotropic cytokine, and persistent activation of the IL6 signaling pathway is implicated in the occurrence and progression of liver cancer." (PMID 39744421, 2025). "The gender disparity in the DEN-induced liver cancer has been associated with high expression of DEN-induced serum IL-6 in males." (PMID 40568073, 2025). "In summary, the nomogram prediction model based on serum CD147, IL-6, and other risk factors has high diagnostic value for the invasion and metastasis of primary liver cancer." (PMID 40919145, 2025). "According to studies, tumor-derived exosome miRNA-1247-3p can activate tumor-associated fibroblasts, causing them to produce cytokines such as IL-6 and IL-8, which promotes lung metastasis of liver cancer." (PMID 39187523, 2024). "At the same time, CRP, another significant indicator of inflammation dependent on IL-6 expression, is associated with inflammatory liver damage and liver cancer progression." (PMID 38166634, 2024). "Chronic inflammation, a known risk factor for liver cancer, was supported by elevated IL-6 and TNF-α protein levels in mouse serum." (PMID 39056720, 2024). "In this study, we used HLJ1-knockout (Dnajb4–/–) mice and demonstrated that HLJ1 deficiency leads to hepatic gene signatures linked to chemical-induced liver cancer and IL-6/STAT3 signaling." (PMID 39738726, 2024). "Using whole-genome transcriptomic analysis, we demonstrate that HLJ1 deficiency in mice results in altered gene signatures enriched in pathways associated with chemically induced liver cancer and IL-6/STAT3 signaling activation." (PMID 39738726, 2024). "Previously, elevated IL‐6 was shown to be correlated with the susceptibility and incidence of liver cancer in male mice." (PMID 37326149, 2023). "It has been reported that oestrogen-mediated inhibition of interleukin-6 (IL-6) reduces the risk of liver cancer in women." (PMID 37752418, 2023). "Its traditional functions include infection defense and hepatocyte homeostasis, as well as acting as a mitogen; nevertheless, inappropriate or persistent IL-6 signaling can cause inflammatory disorders, metabolic problems, and even liver cancer." (PMID 37798688, 2023). "This study aims to assess the risk of developing hepatic cancer in HCV-infected patients due to the presence of IL-6–174 G/C and TGFβ-1 +29 C/T polymorphisms." (PMID 36215278, 2022). "Studies have shown that the stimulation of interleukin 6 (IL-6) can cause the spread of liver cancer cells, which are mainly caused by the promotion of lncTCF7 expression through the transcription (STAT) signaling pathway." (PMID 35155682, 2022). "Hypomethylation of the IL-6 promoter is also an independent risk factor that affects the development of liver cancer." (PMID 35359408, 2022). "A recent study demonstrated that the IL6/STAT3 signaling cascade mainly causes CD133 + enrichment in liver cancer." (PMID 34368140, 2021). "Together, those results implicated that Kyn promoted IL-6 expression through AhR to promote liver cancer progression." (PMID 34657635, 2021). "For more information about the downstream pathways associated with CD90‐mediated stem cell functioning in liver cancer cells, the IL6/JAK2 signalling components and STAT3 phosphorylation were further analysed in liver cancer cells 97L and Huh7." (PMID 29722127, 2018). "Because Mdr2 ablation leads to early spontaneous carcinogenesis at 4–6 months of age, we examined the development of liver cancer at 6 months of age in IL-6-deficient and WT mice." (PMID 27589954, 2016). "We elucidated the occurrence and development of liver cancer in response to toxin challenge and mdr2 gene ablation in the monocyte-specific IL-6-deficient mice." (PMID 27589954, 2016).
liver cancer (continued). "Under the principles of Mendelian randomization, a reduction of 1 pg/mL in circulating IL-6 was significantly associated with an 12% reduced risk of liver cancer (95% CI: 0.64 to 0.99)." (PMID 26096712, 2015). "After control for case-control status and established liver cancer risk factors, coffee intake was positively associated with C-peptide and inversely with IL-6, GLDH, ALT, AST, GGT, alkaline phosphatase, total bilirubin, and AFP." (PMID 26561631, 2015). "In further Mendelian randomization analysis, a reduction of 1 pg/mL in circulating IL-6 was significantly associated with an 12% reduced risk of liver cancer." (PMID 26096712, 2015). "It is believed that higher serum levels of IL-6 in male mice contribute to the increased susceptibility to DEN-induced liver cancer in these mice compared with female mice." (PMID 22136659, 2011). "Recently, it was demonstrated that in chemically induced hepatocarcinogenesis in C57Bl/6 mice, the estrogen-mediated inhibition of IL-6 production is responsible for a lower risk of liver cancer in females." (PMID 19340302, 2009). "Moreover, researchers have explored the potential of combining ICIs with therapies targeting cytokines like IL-6, which is heavily implicated in liver cancer progression." (PMID 40544399, 2025). "The medicine may diminish inflammatory cytokine cascades (e.g., TNF-α, IL-6) by reducing glucose levels and enhancing insulin sensitivity, so mitigating liver damage and fibrosis, which elevate the risk of liver cancer." (PMID 40439888, 2025). "Therefore, adding estrogen to male mice can inhibit IL-6 production and reduce the risk of liver cancer in men." (PMID 38605023, 2024). "Using cDNA microarray analysis, we demonstrated that HLJ1 deficiency alters hepatic gene signatures associated with chemical-induced liver cancer and IL-6/STAT3 signaling, and HLJ1 knockout mice showed pronounced STAT3 activation in normal liver adjacent to DEN-induced tumors." (PMID 39738726, 2024). "It has been confirmed that the p38 MAPK signaling pathway is associated with EMT and liver cancer metastasis: p38 plays an vital role in regulating IL-6 production and MAPK plays a synergistic role with the transcription factor SNAIL to promote tumor invasion and metastasis." (PMID 37313461, 2023). "IL-6 has been proven to be associated with liver cancer in numerous studies." (PMID 35359408, 2022). "Elevated IL-6 concentrations are a risk factor for liver cancer." (PMID 36560418, 2022). "Furthermore, hepcidin expression was tightly associated with BMP6 proteins and IL6 cytokines, as well as anti-cancer immune infiltration in liver cancer tissues." (PMID 34277457, 2021). "BMP6/IL6 pathway insufficiency is a potential cause of hepcidin downregulation in liver cancers." (PMID 34277457, 2021). "Together, our study showed that the TDO2/Kyn/AhR/IL-6 signaling pathway was a novel mechanism underlying the malignancy of liver cancer, and suggested that AhR signals might be a valuable therapeutic target for tumor therapy." (PMID 34657635, 2021). "It was likely that both STAT3 and NF-kB signals were required for IL-6 induced liver cancer progression, though the specific underlying mechanism remains unclear." (PMID 34657635, 2021). "Furthermore, from the public clinical microarray database of TCGA, we found that the expression of BMP2 in liver cancer tissues was associated with Arg1 and IL6, the activation marker of MDSCs." (PMID 32195173, 2020). "Notably, upregulation of inflammatory cytokines represents an important factor in causing liver cancer, and IL6 is believed to play a key role in inflammation-associated tumorigenesis." (PMID 32610656, 2020). "The most noteworthy finding of this study was that long-term genetically-reduced circulating IL-6 might be causally associated with a lower risk of liver cancer." (PMID 26096712, 2015). "Long-term genetically-reduced circulating IL-6 might be causally associated with a lower risk of liver cancer." (PMID 26096712, 2015).
liver cancer (continued). "Furthermore, the high serum level of IL-6 has been shown to be closely associated with the progression of liver cancer." (PMID 24348829, 2014). "Inflammatory markers such as C-reactive protein (CRP) and interleukin-6 (IL-6) are often elevated in liver cancer, making it difficult to monitor for bacterial infection." (PMID 40419900, 2025). "The results of this study showed that intact capsule, tumor > 5 cm, AFP, CAR, CD147, and IL-6 were all independent factors affecting the invasion and metastasis of primary liver cancer." (PMID 40919145, 2025). "These factors further drive liver cancer progression by inducing the release of pro-inflammatory cytokines, including Interleukin-1β (IL-1β) and IL-6, and modulating oncogene Gro-α expression." (PMID 41395459, 2025). "Recent studies have identified some factors released by CAFs in liver cancer, like IL-6, CXCL12, IL-8, and CCL-2, which inhibit CD8+ T cells and facilitate M2 macrophage differentiation." (PMID 40755769, 2025). "IL-6 can also inhibit the activity of immune cells, making it easier for liver cancer cells to escape from the immune monitoring and removal of the body, thereby accelerating the process of invasion and metastasis." (PMID 40919145, 2025). "Animal models show that pro-inflammatory cytokines, such as lymphotoxin-α, tumor necrosis factor-α (TNF-α), and interleukin-6 (IL-6), promote liver cancer and aggressive tumor traits." (PMID 41041128, 2025). "Elevated levels of IL-6 have been associated with worse prognoses in patients with HCC, emphasizing its role as a key player in liver cancer progression." (PMID 40869967, 2025). "Together, these observations implicate age-associated expression of hepatocyte CD44, known for its role in liver cancer initiation, in activation of the immune suppressive IL6/JAK/STAT3 pathway and T cell dysfunction in the aged liver." (PMID 41509421, 2025). "Logistic multivariate analysis showed that intact capsule, tumor > 5 cm, AFP, CAR, CD147, and IL-6 were all independent factors affecting the invasion and metastasis of primary liver cancer (p < 0.05)." (PMID 40919145, 2025). "IL-6 can promote angiogenesis in the tumor microenvironment and provide more nutrition and oxygen support for liver cancer cells, which is conducive to their growth and metastasis." (PMID 40919145, 2025). "Studies have shown that C-reactive protein and IL-6 levels are significantly positively correlated with the severity of inflammation, and IL-6 induces C-reactive protein expression in liver cancer cells." (PMID 38769368, 2024). "This study demonstrates that IL-6 acts as a pro-inflammatory cytokine and is beneficial to the development of liver cancer in a DEN-induced mouse HCC model." (PMID 38605023, 2024). "The development of liver cancer stem cells (LCSCs) and the preservation of their characteristics during the liver cancer process involve several signaling pathways, including Wnt/Catenin, Hippo, IL-6/STAT3, MAPK, and Notch pathways." (PMID 39494254, 2024). "TG2 has been shown to promote epithelial to mesenchymal transition of liver cancer cells and cancer progression in an IL6/signal transducer and activator of transcription (STAT) 3 mediated pathway." (PMID 38650935, 2024). "Kupffer cells and inflammatory monocytes also play a role in promoting the transition from chronic hepatitis to liver cancer by releasing proinflammatory cytokines such as TNFα, IL-6, and monocyte chemoattractant protein 1 (MCP-1)." (PMID 39000296, 2024). "From a mechanistic point of view, the chemical carcinogen DEN induces liver cancer by promoting the production of IL-6 in Kupffer cells (KCs) in a toll-like receptor adapter protein MyD88-dependent manner." (PMID 38605023, 2024). "CHI3L1 promotes an inflammatory response in liver cancer cells by activating signaling pathways that induce the production of proinflammatory cytokines, such as IL-6 and TNF-α." (PMID 38177294, 2024).
liver cancer (continued). "A total of 86 targets of the herbal compound for liver cancer were obtained, mainly five core targets of IL-6, ESR1, JUN, IL1β, and MMP9." (PMID 37680619, 2023). "PFKFB3, the key factor in the Warburg effect, was overexpressed in liver cancer, and the regulation of IL-6/HIF-1α/PFKFB3 played an important role in dosage-specific pro-invasive effect of sorafenib." (PMID 37476196, 2023). "One of the mechanisms that protect biologically female liver cancer patients is estrogen-mediated blockage of IL-6 by the Kupffer cells of the liver." (PMID 37666817, 2023). "The data reveal that PT upregulated the level of IL-6 in liver cancer cells analyzed using IF and real-time RT PCR at 24 and 48 h after PT." (PMID 36672266, 2023). "By activating NF-κB in Mφ, Tim-3 promotes IL-6 releasing, and the multiplication of liver cancer cells is, therefore, enhanced." (PMID 37663266, 2023). "In classic treatment for liver cancer, sorafenib can reverse resistance by blocking the IL-6 and AKT pathways." (PMID 37990309, 2023). "Targeted deletion of IL-6 in macrophages reduced the incidence of spontaneous liver cancer by disrupting the IL-6/STAT3 axis, promoting cell proliferation and cell death resistance." (PMID 35409139, 2022). "Interleukin-6 (IL-6) has been confirmed to participate in the occurrence of HBV-related liver cancer by activating the STAT3 pathway." (PMID 35359408, 2022). "At the same time, the level of IL-6 promoter methylation was also an independent factor in the development of liver cancer." (PMID 35359408, 2022). "As an inflammation-related tumor, the occurrence of liver cancer is accompanied by a large number of inflammatory components, including IL-6." (PMID 35432524, 2022). "variant Indonesia and Philippines against the expression of IL-6 and STAT3 was examined in liver cancer cell line." (PMID 37829248, 2022). "In summary, our study demonstrated that RasGRP1 is an essential regulator that promotes the inflammatory response by increasing IL-6 production and suppressing liver cancer cell growth via inhibition of EGFR-SOS1-Ras-AKT signalling pathway activation." (PMID 36385095, 2022). "Previous studies have also reported that HCC is an inflammation-related cancer and that IL-6-dependent STAT3 activation is a critical instigator of inflammation-induced liver cancer." (PMID 35862398, 2022). "Saffron can inhibit the activation of STAT3 pathway and non-receptor protein tyrosine kinase by inhibiting the DNA binding activity of STAT3 in IL-6 stimulated liver cancer cells." (PMID 36591515, 2022). "Altogether, we conclude that decreased RIG-I in liver cancer progenitor HcPCs promotes their response to IL-6, which drives the progression from HcPCs to fully established HCC in the DEN model mimicking necroinflammation-induced hepatocarcinogenesis." (PMID 36333807, 2022). "Large amounts of IL‐6 are secreted from BMSCs to stimulate IL‐6/STAT3 pathway signal transduction and significantly increase the invasion rate of liver cancer cells, which can be reversed by anti‐IL‐6 antibodies." (PMID 34981659, 2022). "The level of IL-6 promoter methylation, an independent factor in the development of liver cancer, is negatively correlated with the IL-6 mRNA level." (PMID 35359408, 2022). "A lncRNA down-regulated in liver cancer stem cells (lncDILC) has been shown to interfere with NF-κB-mediated IL-6 expression via inhibiting STAT3 signaling, and thus has prognostic value for patients with HCC." (PMID 35141283, 2022). "At the same time, the content of IL-1α, IL-12 P70, TNF α, IL-1β and IL-6 was significantly reduced, and the content of IL-10 was significantly increased like in the previous liver cancer model." (PMID 34976592, 2022). "In vitro experiments using liver cancer cells underline that STAT3 regulates cell survival and that inhibition of this molecule blocks the anti-apoptotic activity of IL-6 on these cells." (PMID 32820432, 2021).